GSTP1 (glutathione S-transferase pi 1)
Diseases named in the same sentence as GSTP1 in open-access papers (continued):
Sharing a sentence is not in itself a finding about the gene and the disease.
prostate carcinoma (continued). "To investigate whether DNA methylation levels at the GSTP1 promoter region are associated with prostate cancer survival, we first re‐examined a published, in‐house whole genome bisulphite sequencing (WGBS) dataset derived from FFPE RP samples." (PMID 39744075, 2024). "Furthermore, DNA methylation differences among CTC metastatic castration-resistant prostate cancer revealed that glutathione s-transferase pi 1 and Ras association domain-containing protein 1A methylation in EVs were correlated with overall survival." (PMID 39062561, 2024). "Subsequently, GSTP1 is methylated, its transcription is inhibited, and the inactivation of GSTP1 increases the sensitivity of normal cells to oxidative stress and the risk of prostate cancer." (PMID 36882835, 2023). "Carriers of the GSTP1*C haplotype, represented by both variant alleles (GSTP1*Val rs1695 + GSTP1*Val rs1138272), had a 5.46-times higher risk of development of prostate cancer compared to individuals with the most frequent haplotype (OR = 5.46, 95%CI = 2.56–11.65, p < 0.001)." (PMID 32183092, 2020). "The goal of this study was to determine whether the GSTM1, GSTT1, and GSTP1 polymorphisms can modify the risk of developing prostate cancer." (PMID 32212077, 2020). "Therefore, we performed a comprehensive analysis of GSTM1 and GSTT1 deletion polymorphisms, as well as of GSTP1 rs1138272 and GSTP1*IIe105Val rs1695 polymorphisms in a cohort of 237 prostate cancer cases and 236 age-matched controls." (PMID 32183092, 2020). "The fact that IGF2-DMR0 hypomethylation goes along with GSTP1 hypermethylation suggests that IGF2-DMR0 hypomethylation could be also considered for risk assessments of prostate cancer." (PMID 29017567, 2017). "Firstly, GSTP1 methylation may be ERβ mediated as studies of prostate cancer lines show that the ERβ/eNOS complex causes GSTP1 repression by local chromatin remodelling following recruitment to estrogen responsive elements." (PMID 28893223, 2017). "GSTP1 methylation is frequently associated with tumor development or poor prognosis in a wide range of tumors such as neuroblastoma, hepatocellular carcinoma, endometrial, breast, and prostate cancers (PCa)." (PMID 27594734, 2016). "For example, DNA hypermethylation of the glutathione S-transferase pi 1 (GSTP1) gene was correlated with prostate cancer, thus serving as a diagnostic tool, while hypermethylation of O 6-methylguanine-DNA methyltransferase (MGMT) aids in decisions for therapeutic strategies for glioma." (PMID 25076963, 2014). "However, more sophisticated GSTP1–GSTT1 interaction should be considered for future experimental design, which would allow a comprehensive understanding of the association between GSTP1 Ile105Val and prostate cancer risk." (PMID 23977100, 2013). "Given the important functions of GSTP1 gene, it is biologically plausible that GSTP1 Ile105Val polymorphism may modify the risk of low-stage prostate cancer." (PMID 23977100, 2013). "GSTP1 is thought to play an important role in susceptibility to prostate cancer." (PMID 23977100, 2013). "The role of GSTP1 Ile105Val polymorphism might be specific according to low or high-stage of prostate cancer." (PMID 23977100, 2013). "In contrast to most cancers, prostate cancer is associated with marked downregulation of GSTP1." (PMID 23977100, 2013). "Loss of GSTP1 expression by promoter hypermethylation is a major event in prostate cancer in which GSTP1 is found hypermethylated in 73% of cases with a sensitivity of 73%, a specificity of 100%, a positive predictive value (PPV) of 100% and a negative predictive value (NPV) of 78%." (PMID 23873296, 2013). "GSTP1 hypermethylation is observed in 70% of patients with high-grade prostatic intra-epithelial neoplasia (a marker lesion associated with the subsequent development of prostate cancer) and in 90% of patients with prostate cancer." (PMID 21867542, 2011).
prostate carcinoma (continued). "In this study, we demonstrate that 5-aza-CdR, at a dose of 0.5 μM given daily, completely inhibited cell proliferation and induced cell death in prostate cancer cells, and was associated with demethylation of the GSTP1 promoter and re-expression of GSTP1 protein." (PMID 21980513, 2011). "Among epigenetic biomarkers, most reports indicate GSTP1 hypermethylation as the diagnostic marker for prostate cancer; however, NKX2-5, CLSTN1, SPOCK2, SLC16A12, DPYS, and NSE1 also have been reported to be regulated by methylation mechanisms in prostate cancer." (PMID 24213111, 2011). "For instance, through the MeInfoText search, we can find that the abnormal silencing of GSTP1 gene is strongly related to prostate cancer that may be also associated with aberrant methylation of other 20 genes with at least 3 papers." (PMID 18194557, 2008). "In prostate cancer, the loss of expression of GSTP1 is the most common genetic alteration reported." (PMID 18827820, 2008). "Since prostate cancer appears to be uniquely deficient in the phase 2 enzyme GSTP1, a rational prevention strategy might be to compensate for GSTP1 loss by global induction of phase 2 enzymes within the prostate." (PMID 16539699, 2006). "Finally, we found that a high threshold of methylation of GSTP1 is associated with a very high specificity, suggesting that this test could identify missed prostate cancer with a minimal increase in false positives." (PMID 31666119, 2019). "However, we note that the 3rd most significant differentially methylated CpG site (p = 8.03×10−05) was closest to Glutathione-S-Transferase (GSTP1) whose expression is increased by prolonged hypoxia and whose loss of expression correlates with methylation in prostate cancer." (PMID 23236293, 2012). "In summary, the molecular mechanism of GSTP1 in prostate cancer was revealed based on machine learning and single-cell analysis." (PMID 40426879, 2025). "Overall, these data point to distinct epigenetic mechanisms of dysregulation of key prostate cancer biomarkers (GSTP1) including NE (ASCL1, SEZ6L), and luminal (e.g FOLH1) genes." (PMID 40593552, 2025). "The Glutathione S-transferase Pi-1 (GSTP1) gene was lowly expressed in prostate cancer and was able to diagnose prostate cancer more accurately." (PMID 40426879, 2025). "These methods can identify tissue-specific methylation patterns that are highly enriched in cancer, such as those in SEPT9 (colorectal cancer), SHOX2 (lung cancer), and GSTP1 (prostate cancer)." (PMID 41020861, 2025). "In this study, GSTP1 methylation was analyzed in 562 patients with metastatic castration‐resistant prostate cancer treated with docetaxel." (PMID 39783747, 2025). "GSTP1 methylation has been studied since 1994 and is the most frequently alteration observed in prostate cancer." (PMID 39783747, 2025). "In a local cohort (PCa patients n = 31; BPH patients n = 34), GSTP1 methylation was observed in 87% of prostate cancer samples compared to only 12% of BPH samples." (PMID 41008642, 2025). "The most widely studied methylation biomarker in prostate cancer research to date is the Glutathione S‐transferase Pi 1 (GSTP1) gene CpG island promoter region." (PMID 39744075, 2024). "In some cancer there are some epigenetic markers that has been discovered due to the fact that prostate cancers frequently contain methylation of the tumor suppressor genes GSTP1, RASSF1, and APC, these genes are regarded as cancer biomarkers." (PMID 39132504, 2024). "In this second cohort of prostate cancer patients, we used a quantitative MS‐HL assay to measure GSTP1 methylation and perform survival analysis with the endpoints BCR, MR and PCSM." (PMID 39744075, 2024). "The ubiquity of GSTP1 promoter methylation (mGSTP1) in prostate cancer, throughout all stages of disease progression, suggests that it is an early, clonal event in tumourigenesis." (PMID 39744075, 2024).
prostate carcinoma (continued). "Glutathione S-transferase P (GSTP1) is downregulated in prostate cancer and upregulated in many cancer types, e.g., colorectal, thyroid, or breast cancer." (PMID 39201484, 2024). "A previous study measuring DNA methylation at GSTP1, APC, and RASSF1 loci in repeat prostate biopsies identified AA and EA men at risk of high-grade prostate cancer." (PMID 38566104, 2024). "Epigenetic silencing of GSTP1 is a common genetic alteration (>90%) in prostate cancer (Henrique and Jerónimo, 2004)." (PMID 39439891, 2024). "It has been reported that GSTP1-1 inactivation is often observed in human cancers (e.g., liver cancer, breast cancer, prostate cancer, leukemia)." (PMID 39125992, 2024). "Together these results support the concept that GSTP1 methylation is one of the earliest and most common molecular events in prostate cancer, likely due to clonal expansion." (PMID 39744075, 2024). "GSTP1, APC, and RASSF1 are three candidate tumor suppression genes, inactivated by hypermethylation, which have been implicated in higher-risk prostate cancers." (PMID 39202766, 2024). "On performing gene ontology analysis, CpG sites in cluster 2 were found to be related to known genes e.g., RARB, GSTP1, RASSF1, SFRP2, which are implicated in prostate cancer." (PMID 39661598, 2024). "For example, this method has been clinically used to validate the effects of PTGER4/SHOX2 genes in lung cancer, as well as the GSTP1 and GSTP1 genes in prostate cancer." (PMID 36911396, 2023). "The present study provides a reference for the clinical application of GSTP1 methylation in prostate cancer." (PMID 36747996, 2023). "The GSTP1 methylation of prostate cancer has been recommended as an epigenetic marker by many researchers." (PMID 36903908, 2023). "Our meta-analysis showed that the combined sensitivity and specificity of GSTP1 promoter methylation in cfDNA for the diagnosis of prostate cancer were 0.37 (95% CI = 0.23, 0.53) and 0.97 (95% CI = 0.88, 0.99), respectively." (PMID 36747996, 2023). "We compared differences in the incidence of GSTP1 promoter methylation in cfDNA between prostate cancer patients and controls." (PMID 36747996, 2023). "Promoter methylation of glutathione-S-transferase p1 (GSTP1) is related to the occurrence of prostate cancer (PCa), but reports are inconsistent about the accuracy of GSTP1 promoter methylation in PCa diagnosis and prognosis." (PMID 36747996, 2023). "The results showed that specific mutations and SNPs in GSTP1, GSTM1, and GSTT1 have been linked to an increased risk of prostate cancer." (PMID 37175108, 2023). "selected epigenetically altered genes in prostate cancer and found AR, GSTP1, RARB, SPARC, TIMP3, and NKX2-5 to be hypermethylated in AA patients." (PMID 36937425, 2023). "Researchers reported that GSTP1 is hypermethylated in prostate cancer, while benign prostatic hyperplasia and normal prostate cells are hypomethylated." (PMID 36903908, 2023). "A total of 7 of 18 (39%) patients with prostate cancer (as determined by the first biopsy) had detectable GSTP1 methylation in their urine (58% sensitivity among valid cases)." (PMID 39188554, 2023). "Differences in GSTP1 promoter methylation in plasma cfDNA between prostate cancer patients and controls were compared." (PMID 36747996, 2023). "Aberrant methylation of the GSTP1 promoter is not limited to prostate cancer, and it occurs in other cancers, including lung cancer and breast cancer." (PMID 36747996, 2023). "Methylation of the GSTP pi gene (GSTP1) is associated with tumor development including neuroblastoma, hepatocellular carcinoma, and endometrial, breast and prostate cancers." (PMID 36903908, 2023). "The ConfirmMDx, which is based on the evaluation of the promoter methylation levels of three genes, namely GSTP1, APC and RASSF1 in prostate biopsy samples, was designed to identify men at lower risk for prostate cancer, thus avoiding repeated biopsies." (PMID 37511475, 2023).
prostate carcinoma (continued). "An initial study indicated that lycopene does not alter the DNA methylation of glutathione S‐transferase P1 (GSTP1) promoter in LNCaP cell lines of prostate carcinoma." (PMID 37823149, 2023). "This test evaluates the methylation status of several genes known to be frequently found in prostate cancer: Glutathione S-Transferase Pi 1 (GSTP1), Adenomatous Polyposis Coli (APC), and Ras association domain family member 1 (RASSF1)." (PMID 36768533, 2023). "GSTP1 promoter hypermethylation is present in more than 95% of prostate cancers and has previously been used in various biomarker studies." (PMID 35272673, 2022). "In prostatectomy tissues from Black and White men, GSTP1+ prostate cancer was overrepresented among tumors from Black men (9.5% vs. 3.2%)." (PMID 35104804, 2022). "Usually, prostate cancer involves the silencing of GSTP1 and previous studies have shown that lycopene treatment activated the GSTP1 promoter and downregulated DNMT3a in a PC-3 cell line." (PMID 36235389, 2022). "Now, GSTP1 hypermethylation assays are approved and marketed as adjuncts to prostate cancer diagnosis, both for Black and for White men." (PMID 35104804, 2022). "Glutathione S-transferase Pi1 (GSTP1) occurs in the early stage of prostate cancer through methylation inactivation and can be detected in up to 90% of prostate cancer." (PMID 36733811, 2022). "Since its first report, GSTP1 silencing has remained the earliest and most frequent gene function defect in prostate cancer, affecting more than 90% of cases." (PMID 35104804, 2022). "We included primers for four genes in the pre-amplification pool (RASSF1, APC, RARB and GSTP1), which have previously been identified as being methylated in a large percentage of prostate cancers." (PMID 35272673, 2022). "Together these observations suggest a general role for GSTM2 and GSTP1 in controlling genomic integrity, which is counter selected in prostate cancer." (PMID 34871444, 2021). "In this study we comprehensively surveyed the frequency of GSTP1 protein expression in human clinical prostate cancers by IHC using tissue microarrays (TMAs)." (PMID 34191807, 2021). "Rare cases of prostate cancer have been reported that are strongly positive for nuclear p63 staining, and these cases tend to express GSTP1, and at times lack GSTP1 GpG island methylation." (PMID 34191807, 2021). "GSTP1 is a member of the Glutathione-S-transferase (GST) family silenced by CpG island DNA hypermethylation in 90–95% of prostate cancers." (PMID 34191807, 2021). "This is the first report revealing that GSTP1-positive prostate cancers are substantially over-represented among prostate cancers from Black compared to White men." (PMID 34191807, 2021). "In this study, we used a large number of primary untreated prostate cancer cases from prostatectomies (N = 1673) to estimate the percentage of prostatic adenocarcinomas that are positive for GSTP1 protein by IHC." (PMID 34191807, 2021). "Both GSTM2 and GSTP1 promoters were among the top 1% of promoters whose methylation is most strongly correlated with TMB in prostate cancer demonstrating that this association is specific for these genes." (PMID 34871444, 2021). "Previous studies have shown that epigenetic changes can be used as biomarkers for the detection of malignant tumors, such as hypermethylation of GSTP1 (Glutathione S-Transferase Pi 1) in prostate cancer." (PMID 34434284, 2021). "Since RNAscope assays perform less robustly on older prostate cancer specimens, we performed in situ hybridization for GSTP1 mRNA and IHC using a “recent case” TMA consisting of an array from 31 RRP cases (TMA set 5)." (PMID 34191807, 2021). "The aim of this study was to analyze the frequency of polymorphic glutathione S-transferase (GSTM1, GSTT1, GSTP1) in patients with prostate cancer compared with the control group of healthy men from Poland." (PMID 32212077, 2020).
prostate carcinoma (continued). "Since the downregulation of GSTP1 expression is a hallmark of prostate cancer, it may be speculated that polymorphic expression influences tumor development in the early stages of prostate carcinogenesis, due to quantitative and qualitative differences in GSTP1 expression and function, respectively." (PMID 32183092, 2020). "Further, somatic hyper-methylation of GSTP1 was reported in > 7% of prostate cancers and > 1% of breast cancers." (PMID 32859265, 2020). "Background and Objectives: One of the most frequent genetic alterations reported to date in prostate cancer (PC) is aberrant methylation of glutathione transferase P1 (GSTP1)." (PMID 32183092, 2020). "Examples include Glutathione S-transferase pi 1 (GSTP1), involved in DNA protection, androgen receptor (AR), in prostate cancer, estrogen receptor (ER) in breast cancer and adenomatous polyposis coli (APC) in colorectal cancer, among many others." (PMID 32365701, 2020). "The results suggested that GSTP1 promoter methylation is higher in cancer tissue than in benign tissue from the same individual and reduced GSTP1 expression is observed in prostate cancer specimens compared to their benign counterparts." (PMID 31357662, 2019). "For GSTP1, a threshold > 10% revealed an OR of prostate cancer of 9.61 (95% CI: 1.07–86.3) for methylation level, and of 5.10 (95% CI: 1.33–19.6) for the highest methylation level." (PMID 31666119, 2019). "One of the best-characterized epigenetic markers is the hypermethylation of the glutathione S-transferase (GSTP1) gene in the biological fluids of prostate cancer patients." (PMID 31097014, 2019). "This seminal study demonstrated distinct GSTP1 gene promoter methylation of the stromal cells in prostate cancer." (PMID 31627186, 2019). "For example, methylated Glutathione S-transferase Pi 1 (GSTP1) is observed in more than 90% of patient’s sera as an early marker of resistance to treatment in prostate cancer." (PMID 31443448, 2019). "GSTP1 gene expression and GSTP1-1 enzyme activity were studied in human prostate carcinoma cells and human prostate tissue specimens." (PMID 31357662, 2019). "In prostate cancer, pi-class glutathione S-transferase gene (GSTP1) promoter is methylated in >90% cases." (PMID 31627186, 2019). "Detection of GSTP1 methylation in all types of body fluids of prostate cancer patients represents a promising epigenetic biomarker, while the unmethylated promoter allowed to distinguish benign lesions from cancerous transformations." (PMID 31357662, 2019). "In this field, several research works found lower GSTP1 expression in prostate cancer, endometrial cancer, hepatocellular cancer (Li, Li, Gao, & Shi, 2015), and ovarian cancer (Shilpa, Bhagat, Premalata, Pallavi, & Krishnamoorthy, 2014)." (PMID 30043549, 2018). "In castrate-resistant prostate cancer it has been shown, that hypermethylated GSTP1 is a more sensitive predictor for disease progression than the established biomarker; prostate specific antigen (PSA)." (PMID 29467946, 2018). "We also found that methylation of GSTP1 was an important factor involved in prostate cancer development." (PMID 29344347, 2018). "In the prostate cancer cell line LNCaP, the GSTP1 gene is silenced due to the aberrant methylation of its promoter." (PMID 29710398, 2018). "GSTP1 is commonly methylated in prostate cancer tissue, blood, and urine, which has been confirmed in multiple studies." (PMID 29038612, 2017). "The most frequently studied epigenetic marker in prostate cancer is Glutathione S-transferase 1 (GSTP1)." (PMID 29038612, 2017). "Methylation biomarkers have been identified in prostate cancer previously, including promoter segments of GSTP1, RASSF1, and APC, which are used in commercial tissue-based test to identify patients needing repeat biopsies after an initial negative biopsy." (PMID 28412973, 2017).